CTSB (cathepsin B)
Diseases named in the same sentence as CTSB in open-access papers (continued):
Sharing a sentence is not in itself a finding about the gene and the disease.
cancer (continued). "Both CTSB mRNA and full-length CTSB polypeptide are more highly expressed in malignant tumors than in benign tumors or normal." (PMID 30796200, 2019). "Cathepsin B was shown to promote the metastasis of cancer cells by degradation of the surrounding ECM, either directly or via activation of uPA, MMPs, and via inactivation of TIMPs." (PMID 31815017, 2019). "Given the aberrantly high expression of Cathepsin B in cancer cells, the peptide cleavable by this enzyme was selected to link Nuc(T) and Mito(T)." (PMID 31296864, 2019). "This peptide is the result of a pancreatic digestion of β-casein and has been described as a competitive inhibitor for cathepsin B which is upregulated in some cancers." (PMID 31024503, 2019). "By analyzing patient samples, increased protein content or activity of cathepsin B have been detected in ovarian and colorectal cancer." (PMID 31484396, 2019). "Cathepsin B has been identified as a lysosomal protease; however, in cancer cells, cathepsin B is transported to the cell surface." (PMID 30818851, 2019). "In cancer cells, cathepsin B is transported to the cell surface, where it localizes and facilitates the ECM destruction process, orchestrating the protease cascade and directing it towards the invasive fronts of metastatic cells." (PMID 30818851, 2019). "Several clinical studies since then have shown correlations between CTSB expression and cancer progression and clinical outcomes." (PMID 30796200, 2019). "In healthy tissues and peripheral blood, PADM is inactive, and it is only activated in the presence of excess cathepsin B, which is overexpressed on cancer cell membranes." (PMID 31737654, 2019). "Upon exposure to cathepsin B, which is present on cancer cell membranes, the Lys-PABC bond is cleaved, and subsequent self-hydrolysis of PABC allows free ADM to be released." (PMID 31737654, 2019). "In cancer cells, Mito(T)-pep-Nuc(T) is expected to rupture in the Cathepsin B-rich lysosomes, liberating Mito(T) and Nuc(T) with distinct subcellular destinations." (PMID 31296864, 2019). "The MP-cL3 probe selectivity for cathepsin L over cathepsin B is of special importance, as cathepsin B is overexpressed in many types of cancers and masks cathepsin L proteolytic activity, making its analysis more complex." (PMID 29719685, 2018). "In one strategy, PEG was combined with cathepsin B to form a liposomal nanoparticle that facilitates the targeting of cathepsin B expressing cancer cells, allowing the release of a therapeutic payload at a target site." (PMID 30134564, 2018). "Cathepsin B, a lysosomal cysteine protease overexpressed in several cancer tissues, is known to degrade extracellular matrix during invasion and metastasis." (PMID 30413047, 2018). "The expression of cathepsin B and X was detected in stromal cells and cancer cells throughout the GBM sections, whereas cathepsin K expression was more restricted to arteriole-rich regions in the GBM sections." (PMID 30046941, 2018). "Cancer cells can also secrete cathepsin cysteine protease, such as cathepsin B and K. Cathepsin B levels are raised in the serum of cancer patients with different types of cancer." (PMID 30441823, 2018). "It has been reported that cathepsin B promotes cancer cell migration or invasion through proteolysis of extracellular matrix and activation of Toll-like receptor 3 (TLR3) and uPA." (PMID 29455656, 2018). "The localization of cathepsin K was distinctly present in specific cells, whereas cathepsin B and X were present in most cancer cells surrounding the arterioles." (PMID 30046941, 2018). "When a large number of CTSB extravasation in lysosomes exceeds the conventional metabolic requirement of cancer cells, CTSB triggers a series of biological effects, including cell autophagy." (PMID 28881816, 2017).
cancer (continued). "Cathepsin B has been validated as a promising target in the treatment of cancer, using a range of research tools, including cathepsin B-specific inhibitors, siRNAs and cathepsin B knock-down or overexpression mouse models." (PMID 28938624, 2017). "As the strongest cathepsin B inhibitor, CysC was proven to be a pro-apoptotic and growth suppressive factor, and has been applied in the diagnosis and prognosis of some cancers." (PMID 28423738, 2017). "Upregulation of CTSB was found in various cancers as well as in premalignant lesions and other pathological conditions." (PMID 29068414, 2017). "In the MMTV-PyMT mouse model overexpression of human Cathepsin B and Cathepsin L promoted migration and invasion of cancer cells as well as metastasis formation." (PMID 27542270, 2016). "Meanwhile, inhibition of CTSB significantly suppressed CCK production by the cancer cells, further supporting that CTSB regulates CCK secretion." (PMID 26700819, 2016). "These proteases, including the urokinase-type plasminogen activator (uPA), cathepsin B and matrix metalloproteinases (MMPs), have been the subject of intense study in recent years as potential mediators of cancer cell invasion and metastasis." (PMID 27351226, 2016). "In this regard, oncogenic RAS-mediated upregulation of MMP2, MMP9, and cathepsin B has been shown to be particularly important in stimulating cancer cell proteolytic activity and invasion." (PMID 27351226, 2016). "As an intense interest of current research, CTSB has been proposed as a potentially effective biomarker for a variety of cancers." (PMID 26896959, 2016). "Our current work revealed that CTSB has an oncogenic role in hepatocarcinogenesis by facilitating cancer cell migration and invasion." (PMID 26896959, 2016). "Most studies have demonstrated that high CTSB expression is related to tumorigenesis in various human cancers." (PMID 27031837, 2016). "Many studies have been conducted using tissue samples to investigate the expression of cathepsin B and heparanase isoforms in a variety of cancers." (PMID 25351637, 2015). "Overexpression of cathepsin B has been observed in malignant tumors, and specifically in the cells at the invasive edge of these tumors." (PMID 25351637, 2015). "CTSB, one of the most abundant cysteine cathepsins, is upregulated in breast and other cancers and considered to be an attractive molecular target for cancer therapy." (PMID 26562785, 2015). "We suggest that caged inhibitor 2 is a prototype for cathepsin B inhibitors that can control both the site and timing of inhibition in cancer." (PMID 26562785, 2015). "Assembling a peptide‐based Cathepsin B cleavable sensor over a large array of nano­needles allows the discrimination of cancer cells from healthy ones in mixed culture." (PMID 26197973, 2015). "There are substantial clinical and cell biological data linking cysteine cathepsins, foremost cathepsin B (Ctsb) and cathepsin L (Ctsl), to cancer progression and metastasis." (PMID 25744631, 2015). "This regulation of the functional gene is equally critical to cancer cell biology and in the case of cathepsin B, the promotion of cancer metastasis through the hydrolytic activity of this enzyme." (PMID 26473288, 2015). "CTSB and CTSD degrade extracellular matrix proteins, and recently they have been implicated in cancer invasion and metastasis." (PMID 24717913, 2014). "Collectively, these data support the use of CtsB as a target for theranostic applications in cancer." (PMID 24975267, 2014). "Multiple studies report that increased cathepsin B and L expression and activity correlate positively with and are involved in the invasion and metastasis of several cancers." (PMID 24709902, 2014). "During cancer invasion, activated CTSB is over expressed on the exterior membrane of the invading cancer cells, which cleaves the Ac-Phe-Lys dipeptide at the Lys-PABC bond." (PMID 24588871, 2014).
cancer (continued). "Cathepsin B (CtsB) is a lysosomal cysteine proteinase that is specifically translocated to the extracellular milieu during cancer progression." (PMID 24975267, 2014). "CTSB is one of the key enzymes in this critical process, over-expressed in GC as well as other cancers and actively involved in cancer invasion." (PMID 24588871, 2014). "In particular, up-regulation and secretion of CTSB is frequently found in several types of malignant cells and cancers." (PMID 23844232, 2013). "Exogenously overexpressed CTSB increased cancer cell invasion and substrate proteolysis, effects that were inhibited by CST3." (PMID 24357805, 2013). "Nonetheless, we provide strong evidence that the chemoradiotherapeutic activation of the NLRP3 and AIM2 inflammasomes, via cathepsin B and ROS, is likely to emerge as a crucial player in the regulation of cancer immunotherapy." (PMID 23065753, 2012). "Under normal circumstances cathepsin B, a house-keeping enzyme, is located in perinuclear lysosomes but in cancer it is secreted and relocalized to the plasma membrane." (PMID 22168338, 2011). "In cancer cells, CTSB is shuttled to the plasma membrane where it can activate receptor-bound pro-urokinase-type plasminogen activator (pro-uPA)." (PMID 21199580, 2011). "Specifically, CTSB is involved in proteolytic pathways that lead to the degradation of ECM proteins thereby promoting cancer cell motility and invasion." (PMID 21199580, 2011). "A positive correlation between CTSB expression and the metastasis of carcinoma cells to lymph nodes has previously been reported in breast, prostate and gastric cancers." (PMID 21199580, 2011). "Previously, we found that CTSB is localized to caveolar membrane microdomains in cancer cell lines including IBC, and therefore, we also examined the expression of caveolin-1 (cav-1), a structural protein of caveolae in IBC versus non-IBC tissues." (PMID 21199580, 2011). "Cathepsin B (CTSB), a lysosomal cysteine protease, has been shown to be a contributor to the progression and invasion of various types of cancer." (PMID 21199580, 2011). "Several protease targeted drugs are routinely used in the clinic, for example, ACE inhibitors, and others are in pre-clinical development, including neutralizing antibodies against both cathepsin B and uPA for cancer treatment." (PMID 22093547, 2011). "Our results revealed a statistically significant positive correlation only between the level of CTSB expression in IBC carcinoma cells and the number of positive metastatic lymph nodes (P = 0.0478)." (PMID 21199580, 2011). "Transport of cathepsin B in normal thyroid epithelial and carcinoma cells was investigated through immunolocalization of endogenous cathepsin B in combination with probing protease activity." (PMID 21835049, 2011). "The possible link between cathepsins and cancer and the role of cathepsin B in metastatic potential was postulated since many years." (PMID 20684763, 2010). "Cathepsin B (catB) is a promising target for anti-cancer drug design due to its implication in several steps of tumorigenesis." (PMID 21210971, 2010). "Among the CTSs, CTSB has been investigated most intensively and appears to play a role in cancer based on its increased expression in various human cancers." (PMID 20727192, 2010). "We detected variations in quantity of cathepsin D, cathepsin B, squamous cell carcinoma antigen, γ synuclein, cytokeratin 19 and other proteins that have been reported to play a role in cancer etiology." (PMID 18416831, 2008). "Therefore, CtsB, through the proteolytic degradation of p27Kip1, promotes the accumulation of cyclin B1, thus facilitating cancer cell proliferation." (PMID 39851495, 2025). "CTSB has been involved in the progression of apoptosis, autophagy, and certain types of cancer." (PMID 40950552, 2025). "Recent works are starting to reveal the role of CtsB in the onset and progression of cancer." (PMID 39851495, 2025).
cancer (continued). "CTSB also displays a dual role in apoptosis, capable of promoting cell death under regulated circumstances or enhancing survival by initiating autophagy in cancer cells." (PMID 40007784, 2025). "Probe designed to be cleaved by cathepsin B showed the strongest discrimination between cancer and control samples, while probes designed to be cleaved by ubiquitin-specific peptidase 15 and plasmin were identified as the most informative subtype-specific markers for UGIC and CRC, respectively." (PMID 40890441, 2025). "Notably, various lysosome specific proteins (LAMP-1/5) and enzymes (CTSB/D/F/G/S/W) were also found to be expressed significantly lower in FA SCC cancers." (PMID 41188232, 2025). "Furthermore, the scAtezo-Pmod2-2 remained unaltered upon incubation with cathepsin B, a protease upregulated in certain cancers that displays endopeptidase activity at neutral pH42." (PMID 41291002, 2025). "So, we observed the activity of cathepsin B in cancer cells using immunofluorescence staining." (PMID 39743555, 2025). "We wondered if BEA could inhibit CTSB in immune cells relevant for anti‐cancer immunotherapy approaches such as DCs." (PMID 40411408, 2025). "DKK1, CTSB, CTSD, and CAPG are also associated with the metastatic potential of cancer." (PMID 37439806, 2024). "Moreover, elevated cathepsin B levels have been observed in various pathological conditions, including inflammation, infection, and cancer." (PMID 39359476, 2024). "Inhibition of cathepsin B activity has potential therapeutic implications in cancer treatment." (PMID 38500921, 2024). "The inverse MR results showed no significant causal effect between UL (all cancers excluded) and CTSB (OR = 0.89, 95%CI [0.79, 1.00], P = 0.060)." (PMID 39264885, 2024). "CTSB is increasingly recognized as a potential therapeutic target in cancer treatment." (PMID 39264885, 2024). "Studies have highlighted the overexpression of CTSB in the early stages of various cancer types." (PMID 39264885, 2024). "In addition, pro-drugs and other target therapeutic agents that respond to cathepsin B have been proposed and used in cancer treatment, and some of them are already on the market." (PMID 38500921, 2024). "Combining cathepsin B inhibitors with other cancer therapies may enhance their efficacy in treating cancer." (PMID 38500921, 2024). "In addition, the transcription factor E2F1, known for its regulatory role in CTSB expression in other cancer types, emerges as a potential participant in OSCC." (PMID 38500921, 2024). "Through hydrophobic interactions and π–π stacking, peptide-modified prodrugs self-assemble into cancer-activating Dox prodrug nanoparticles (CAP-NPs) that are specifically degraded into cytotoxic Dox molecules by cathepsin B, an enzyme overexpressed in cancer cells." (PMID 38255307, 2024). "Furthermore, CTSB plays a role in the development of cancer as well as in conditions such as lung and cardiovascular disorders." (PMID 39064733, 2024). "In addition, in some cancer cells, CTSB is localized to the cell surface and secreted into the extracellular environment." (PMID 37576397, 2023). "Upregulation of CtsB is tightly correlated with the activity of other proteases, which were shown to favor cancer progression, like the urokinase plasminogen activator (uPA)/plasminogen/plasmin, matrix metalloproteinase 9 and overexpression of VEGF-C and TGF-β, resulting in angiogenesis promotion." (PMID 37514035, 2023). "Therefore, ApoLNPs demonstrated their highly specific pro-apoptotic cell death induction in cathepsin B-overexpressing cancer cells." (PMID 37845762, 2023). "In addition to regulating the function of the actin cytoskeleton proteins MARCKS and spectrin in healthy renal epithelial cells, cathepsin B has been studied in cancer and its therapeutic potential has been investigated." (PMID 37239160, 2023). "Targeting and inhibiting cathepsin B in cancer cells could have significant therapeutic implications." (PMID 37111617, 2023).
cancer (continued). "These two short peptide sequencesare well-known substrates of matrix metalloproteinase-2 (MMP-2) andcathepsin B, respectively, both of which are overexpressed in a widerange of cancer cells either extracellularly (for MMP-2) or intracellularly(for cathepsin B)." (PMID 36961946, 2023). "Cancer cells will undergo apoptosis when cathepsin B inhibits TLR3-mediated apoptosis." (PMID 37334378, 2023). "The role of CTSB in the TGF-β1 signaling pathway is also a key signal that triggers EMT in cancer." (PMID 37576397, 2023). "In return, CTSB promotes the secretion of CCK by cancer cells." (PMID 37576397, 2023). "To determine the role of CTSB in BMI1 mediated cancer cell properties, we genetically modified CTSB expression in WBBMI1/PLCBMI and BMI1 depleted MHCC97H cells, indicating that neither CTSB depletion/overexpression affected the proliferation and colony formation in these cells." (PMID 37923799, 2023). "Additionally, the malignant properties of cancer cells must be identified as a function of CtsB overexpression, even though this enzyme is ubiquitous and expressed at varying levels in all cancer cells." (PMID 37514035, 2023). "However, the significant expression of CtsB in cancer tissue also provides therapeutic avenues designed to leverage the proteolytic activity of this enzyme." (PMID 37514035, 2023). "Evidence revealed that overexpression of CTSB could initiate cell invasion and metastasis in several cancers." (PMID 36510340, 2023). "Lysosomal CTSB was known to be secreted by cancer cells, which could degrade extracellular matrix as well as breaking down cell adhesion and junction to stimulate cancer cell invasiveness." (PMID 37923799, 2023). "Several mechanisms for cathepsin B’s contribution to cancer development were demonstrated with in vitro and in vivo models, and its ability to proteolytically interfere with the apoptotic pathway was proposed to be a significant aspect of its oncogenic potential." (PMID 39816815, 2023). "CTSB has been described as a “multifunctional” enzyme in cancer." (PMID 37576397, 2023). "The efficacy of CtsB inhibition has been tested in ameliorating a spinal cord injury by inhibiting macrophage ferroptosis and treating cancer through the development of small molecules, such as the Nostoc-species-derived oxadiazine Nocuolin A, or biologics based on peptides." (PMID 37514035, 2023). "Moreover, CTSB/L have been reported to serve as oncogenes, which is in accordance with our result that expressions of CTSB/L in cancer are generally higher than the matched normal tissues." (PMID 35155389, 2022). "Interestingly, CTSB/L expressions were significantly correlated with immune cell infiltration in manifold cancer tissues and their corresponding normal tissues." (PMID 35155389, 2022). "By combining the antitumor activity of chemotherapeutic drugs and the tumor selectivity of antibodies, ADCs display a wider window for cancer chemotherapy than chemotherapeutic drugs alone.[2a] ADCs with cathepsin B‐cleavable linkers are particularly effective, having high plasma stability." (PMID 34953094, 2022). "In addition, the CTSB mRNA expression levels between different cancer tissues and matched normal tissues (TCGA normal + GTEx normal) were compared by using GEPIA2." (PMID 35155389, 2022). "Thereby, a vigorous ratiometric fluorescent method could be achieved by integrating a cancer-targeting recognition moiety to report CTSB activity." (PMID 35401835, 2022). "In silico potential inhibitors of Cathepsin B (CathB) as a cancer biomarker were determined." (PMID 36574159, 2022).